ROBO1 (roundabout guidance receptor 1)
Diseases named in the same sentence as ROBO1 in open-access papers (continued):
Sharing a sentence is not in itself a finding about the gene and the disease.
epilepsy (4 papers, 2020 to 2023). A brain disorder characterized by episodes of abnormally increased neuronal discharge resulting in transient episodes of sensory or motor neurological dysfunction, or psychic dysfunction. "We speculate that Robo1 has been implicated in the development and progression of epilepsy through its effects on dendritic spine morphology and density." (PMID 38680506, 2023). "Changes in the expression of Robo1 in epilepsy could be either a phenomenon caused after epileptogenesis or a cause of seizures." (PMID 38680506, 2023). "Likewise, ROBO1 which was identified in ASD with comorbid epilepsy was implicated in developmental dyslexia and dysfunction of language acquisition system." (PMID 32477112, 2020). "To further precisely localize Robo1 in epilepsy, we examined the cellular localization of Robo1 in epileptic brain tissues by immunofluorescence double antibody labeling." (PMID 38680506, 2023). "It was found that Robo1 was basically expressed in the hippocampus of mice, suggesting that Robo1 is also involved in the pathogenesis of epilepsy." (PMID 38680506, 2023). "In this study, we first predetected the expression of Robo1 in the hippocampus of mice in a model of chronic pentatetrazin‐ignited epilepsy." (PMID 38680506, 2023). "In this study, we aimed to explore the mechanism of Robo1 in epilepsy." (PMID 38680506, 2023). "Then, we report a novel finding that the knockout of Robo1 by LV reduces seizure latency and seizure grade, so the knockout affects the morphology and density of dendritic spines and contributes to the development of epilepsy." (PMID 38680506, 2023). "Taken together, Robo1 expression is increased in the epileptic brain and colocalizes with neurons in the epilepsy‐related hippocampal regions, suggesting that Robo1 may be involved in epileptic activity." (PMID 38680506, 2023). "However, although Robo1 is one of the important components of axon guidance, the role of Robo1 in epilepsy remains unclear." (PMID 38680506, 2023). "Notably biallelic sequence variants within ROBO1 are associated with a neurodevelopmental disorder displaying many of the cardinal features seen in SNIP1-related disorder including neurodevelopmental delay, white matter abnormalities, epilepsy, autistic features, VSD and tetralogy of Fallot." (PMID 34570759, 2021).
neuroblastoma (4 papers, 2011 to 2025). Neuroblastoma (NB) is the most common solid, extracranial childhood tumor. "In neuroblastoma, EphB4 and CLDN1 are not expressed, but in addition to LAT1, some ROBO1 is expressed." (PMID 40076777, 2025).
ovarian carcinoma (4 papers, 2011 to 2025). A malignant neoplasm originating from the surface ovarian epithelium. "This knowledge gap served as a driving force for our study, prompting us to investigate the expression of ROBO1 in clinical ovarian cancer samples and to devise a safe and efficient treatment strategy for ovarian cancer patients exhibiting ROBO1 expression." (PMID 39069888, 2024). "Nonetheless, our findings still underscore the potential of ROBO1-NK cells to effectively target tumor tissues at the organoid level, exemplified by our observations in the two ovarian cancer samples." (PMID 39069888, 2024). "In conclusion, our study has unveiled a promising therapeutic strategy for ovarian cancer patients by targeting the novel biomarker, ROBO1." (PMID 39069888, 2024). "Through IHC analysis, cytoplasmic and membrane expression of ROBO1 was observed in ovarian cancer cells, with some cells exhibiting robust positive ROBO1 expression surrounding the membrane." (PMID 39069888, 2024). "In the clinical context, four out of fifteen ovarian cancer samples were identified as displaying positive ROBO1 expression." (PMID 39069888, 2024). "We fully acknowledged the inherent heterogeneity of ROBO-1 expression within the samples of ovarian cancer patients." (PMID 39069888, 2024). "Our results inspire confidence in the future application of ROBO1-NK cells as a personalized and efficacious treatment approach for ovarian cancer patients." (PMID 39069888, 2024). "Based on these promising findings, we obtained four ROBO1-positive samples from ovarian cancer patients and derived primary tumor cells to evaluate the effectiveness of ROBO1-NK cells." (PMID 39069888, 2024). "In this study, we conducted a collection of peripheral blood mononuclear cells (PBMCs) from ovarian cancer patients exhibiting positive ROBO1 expression in their tumor tissues." (PMID 39069888, 2024). "Through successful development and characterization, we have demonstrated the efficacy of ROBO1-NK cells derived from patients' own PBMCs in effectively lysing ovarian cancer cell lines, primary ovarian cancer cells, and tumor organoids." (PMID 39069888, 2024). "The present study elucidated a groundbreaking approach in the field of immunotherapy, wherein autologous PBMC-derived CAR NK cells targeting ROBO1 were employed for the treatment of ovarian cancer." (PMID 39069888, 2024). "Despite the extensive research on the biomarker ROBO1 in various tumor types, its involvement in ovarian cancer pathogenesis remains inadequately explored." (PMID 39069888, 2024). "In this study, the focus was directed toward ROBO1, a molecule known to play a pivotal role in cancer angiogenesis and metastasis, while limited investigation in the context of ovarian cancer." (PMID 39069888, 2024). "This study described a novel, autolougs immunotherapy, PBMC-derived ROBO1-targeted CAR NK cells for ovarian cancer treatment." (PMID 39069888, 2024). "Considering these findings, it is imperative to develop more effective immunotherapy strategies targeting ROBO1 in clinical ovarian cancer." (PMID 39069888, 2024). "Furthermore, ROBO1 expression has been detected in the SKOV-3 ovarian cancer cell line, indicating its involvement in malignant progression." (PMID 39069888, 2024). "The investigation highlights the potential of ROBO1 as an immunotherapy target in ovarian cancer." (PMID 39069888, 2024). "Nevertheless, the clinical significance of ROBO1 in ovarian cancer is inadequately explored." (PMID 39069888, 2024). "Surprisingly, the ROBO1-NK cells exhibited a substantially accelerated rate of lysing the ovarian cancer organoids compared with primary cancer cells in this investigation, achieving lysis within a mere 12 h in contrast to the 48 h needed for primary cancer cell lysis." (PMID 39069888, 2024).
ovarian carcinoma (continued). "In contrast, ROBO1-NK cells can still effectively target ovarian cancer cells by virtue of their ROBO1-CAR, which recognizes the ROBO1 protein expressed on the membrane of ovarian cancer cells." (PMID 39069888, 2024). "This study introduces a novel autologous immunotherapy approach for ovarian cancer treatment, utilizing PBMC-derived ROBO1-targeted CAR NK cells." (PMID 39069888, 2024). "Basal SLIT2, SLIT3, ROBO1, ROBO2 and ROBO4 expression was lower in primary cultures of ovarian cancer epithelial cells when compared to normal OSE (P<0.05) and in poorly differentiated SKOV-3 cells compared to the more differentiated PEO-14 cells (P<0.05)." (PMID 22132142, 2011). "Compared with primary NK cells without ROBO1-CAR modification, ROBO1-NK cells exhibited higher efficiency in eradicating primary ovarian cancer cells and lysing ovarian tumor organoids." (PMID 41181137, 2025). "Through the utilization of immunohistochemistry (IHC) analyses, it was observed that not all patients diagnosed with ovarian cancer exhibited the expression of ROBO1 within their respective tumor tissues." (PMID 39069888, 2024).
pancreatic ductal adenocarcinoma (4 papers, 2023 to 2025). An infiltrating adenocarcinoma that arises from the epithelial cells of the pancreas. "Notably, three phase I/II clinical trials (NCT03940820, NCT03941457, NCT03931720) conducted in Chinese cohorts evaluated allogeneic ROBO1-specific CAR-NK-92 cell immunotherapy for pancreatic ductal adenocarcinoma (PDAC) and ROBO1-expressing solid tumors." (PMID 40852706, 2025).
schizophrenia (4 papers, 2011 to 2025). A major psychotic disorder characterized by abnormalities in the perception or expression of reality. "For example, guidance receptors such as Robo1/2 and ErBb4 have been linked to neurodevelopmental disorders, such as Autism Spectrum Disorder for Robo1/2 and schizophrenia and bipolar disorder for ErbB4." (PMID 40661145, 2025). "We, however, also found a duplication disrupting ROBO1 in a schizophrenia-affected subject from our own case–control sample." (PMID 26460480, 2015). "As regards rare CNVs in our own schizophrenia case–control sample, we found two partial deletions of the DLG2 locus (one case and one control) and one case duplication affecting the ROBO1 locus; all three CNVs were exon-disrupting." (PMID 26460480, 2015).
asthma (3 papers, 2011 to 2024). "Among the asthma genes identified in genome wide association studies, ROBO1, RORA, HLA-DQB1, IL2RB and PDE10A were differentially expressed during human lung development." (PMID 21699702, 2011). "Among the asthma genes identified in GWAS, ROBO1, RORA, HLA-DQB1, IL2RB and PDE10A showed most significant evidence of involvement in lung development (all adjusted p < 0.001 for differential expression)." (PMID 21699702, 2011). "Among genes identified in asthma GWAS, ROBO1, RORA, HLA-DQB1, IL2RB and PDE10A showed most consistent expression patterns and from asthma candidate genes, e.g. NOD1, EDN1, CCL5 and HLA-G were identified." (PMID 21699702, 2011). "Among the GWAS asthma genes, ROBO1, RORA, HLA-DQB1, IL2RB and PDE10A were differentially expressed in the human data." (PMID 21699702, 2011).
colon cancer (3 papers, 2010 to 2023). "SLIT2 appears to be a candidate for a colon cancer suppressed gene, since it is often inactivated by LoH and hypermethylation and its receptor, ROBO1, has been implicated in colon cancer, although the underlying mechanism of the SLIT-ROBO involved tumor growth remains obscure." (PMID 20187943, 2010). "Additionally, in colon cancer, SLIT2/ROBO1 has been shown to encourage tumor growth." (PMID 38304289, 2023).
diabetic retinopathy (3 papers, 2011 to 2022). "Studies have shown that Slit-2 is expressed in the fibrous vascular membrane of diabetic patients, and Slit-2/Robo1 signaling has been proved to contribute to the development of diabetic retinopathy." (PMID 35813663, 2022). "The alteration of Slit2 and Robo1 expression in the retinas of diabetic rats and patients with proliferative diabetic retinopathy suggests a role for the Slit-Robo signal in the various stages diabetic retinopathy." (PMID 28973045, 2017).
esophageal cancer (3 papers, 2016 to 2025). A primary or metastatic malignant neoplasm involving the esophagus. "Cellular experiments demonstrated ROBO1 directly interacted with eukaryotic translation initiation factor 3A (eIF3A) and accelerated its degradation in esophageal cancer cells after irradiation treatment." (PMID 40188129, 2025).
Intellectual disability (3 papers, 2020 to 2024). "Cell cluster-specific Gatad2b dosage-sensitive genes include Frmd4a, associated with intellectual disability and Robo1 that mediates proliferation and neurogenesis in development and is clinically associated with a neurodevelopmental disorder in cluster 0 (Layer II-VI)." (PMID 38238293, 2024).
intestinal cancer (3 papers, 2015 to 2025). "This study has clearly demonstrated an oncogenic role of Slit2/Robo1 signaling during the tumorigenesis and progression of intestinal cancer." (PMID 25605242, 2015). "The fact that activation of Slit2/Robo1 signaling led to an altered epithelial structure in our study further demonstrates that Slit2 can drive the precancerous lesions of the intestine to intestinal cancers." (PMID 25605242, 2015). "These two models can mimic the process of in vivo intestinal tumorigenesis, and allow us to successfully define the expression and function of Slit2/Robo1 signaling during the tumorigenesis and progression of the intestinal cancers." (PMID 25605242, 2015). "In summary, our data have demonstrated that activation of Slit2/Robo1 signaling is critically involved in the intestinal tumorigenesis and Slit2 may constitute a potential biomarker for the early detection and therapy of intestinal cancers." (PMID 25605242, 2015). "The SLIT2/ROBO1 pathway has been shown to be involved in the progression of intrahepatic cholangiocarcinoma (ICC), breast and bowel cancer." (PMID 37059586, 2023).
intestinal tumor (3 papers, 2015 to 2019). "All the results suggested that the specific blocking of Slit2/Robo1 signaling inhibited tumor growth and metastasis during intestinal tumor development." (PMID 31242633, 2019). "We next investigated the impact of Slit2/Robo1 signaling on the initiation and development of intestinal tumors using the Slit2 transgenic (Slit2-Tg) mice model in which Slit2 is genetically overexpressed." (PMID 25605242, 2015). "In this study, we observed that specific blocking Slit2 binding to Robo1 could attenuate tumor growth and metastasis in intestinal tumor mouse models." (PMID 31242633, 2019). "We showed that Slit2 and Robo1 are overexpressed in intestinal tumors and may contribute to tumor generation." (PMID 25605242, 2015). "Along with the increased expression of pSrc (Tyr 416) in the intestinal tumor tissues of the ApcMin/+;Slit2 mice and DMH/DSS-Slit2 mice, activation of Slit2/Robo1 signaling was also found to be associated with a marked decrease in the expression of E-cadherin in the tumor tissues." (PMID 25605242, 2015). "Additionally, ROBO1 activates Wnt/β-catenin signaling pathway in intestinal tumor, thus, functions as a cancer-promoting oncogene." (PMID 26610476, 2015). "Overexpression of Robo1 can be seen in TGF-β and Wnt-induced intestinal tumors." (PMID 31242633, 2019). "According to our previous findings, Slit2/Robo1 signaling might regulate tumor growth by activation of the Wnt pathway, and induce tumor metastasis by TGF-β/Smads signaling and Hakai-mediated EMT during intestinal tumor development." (PMID 31242633, 2019).
invasive breast carcinoma (3 papers, 2004 to 2023). A carcinoma that infiltrates the breast parenchyma. "In mice, Robo1 inactivation produces delayed lung maturation and bronchial hyperplasia and we have demonstrated de novo ROBO1 promoter methylation in 19% primary invasive breast carcinomas and 18% primary clear cell RCC, although somatic mutations were not identified." (PMID 14735202, 2004).
language disorder (3 papers, 2013 to 2024). A category of disorders characterized by an impairment in the development of an individual's language capabilities, which is in contrast to his/her non-verbal intellect. "The genes SEMA6D, AUT2 and ROBO1, OXR1 and MUC6 were reported as interesting candidate genes because potential pathogenic variants co-segregated with the language disorder in affected relatives of the respective probands." (PMID 38298611, 2024). "Finally, among the set of robust candidates for language disorders and language evolution, we have found that ROBO1 is strongly upregulated in the blood of our subject compared to his healthy father and particularly, to his asymptomatic carrier mother." (PMID 29922639, 2018). "For the non-creative group, a deletion at 3p12, locating near to a susceptibility gene for reading and language disorder ROBO1, was more common compared to the creative group (24% non-creative vs. 0% creative)." (PMID 23460800, 2013).
liver cancer (3 papers, 2017 to 2022). An epithelial or non-epithelial malignant neoplasm that arises from the liver. "ROBO1 is known to be expressed in fetal tissues, particularly the nervous system, and was first identified as a tumor-specific antigen in liver cancer in 2006." (PMID 36498797, 2022). "Additionally, the expression of ROBO1 was detected in 1/11 cases (9%), while positive expression of ROBO1 was found in 10/11 cases (91%) of liver cancer tissues." (PMID 33195412, 2020). "CAP2 was coexpressed with TP53BP2, ENA/VASP in the liver cancer, and CFL1, CFL2, DSTN, ACTB, ACTG1, and ROBO1." (PMID 28423713, 2017).
lung adenocarcinoma (3 papers, 2005 to 2025). A carcinoma that arises from the lung and is characterized by the presence of malignant glandular epithelial cells. "Homozygous Robo1/Dutt1 knockout mice are embryonically lethal, but heterozygous mice were found to develop lymphomas and lung adenocarcinomas at high frequency." (PMID 16254601, 2005).
medulloblastoma (3 papers, 2014 to 2024). A malignant, invasive embryonal neoplasm arising from the cerebellum. "Slit2 was also shown to inhibit medulloblastoma cell invasion in multiple models in vitro and this effect was rescued by the ectodomain of Robo1." (PMID 39456164, 2024).
melanoma (3 papers, 2018 to 2025). A malignant, usually aggressive tumor composed of atypical, neoplastic melanocytes. "Four Robo receptors (Robo1 to Robo4) and three Slit ligands (Slit1 to Slit3) are present in melanocyte and melanoma cells, whereas only Robo1, Robo3 and Slit1 are present in E15.5 mouse melanoblasts." (PMID 29769218, 2018).
microtia (3 papers, 2024 to 2025). "Genetic studies have shown that microtia is linked to mutations in ROBO1/ROBO2, HOXA2, SIX1/SIX5, TBX1, or CHUK in humans." (PMID 38690987, 2024). "Scholars have also found that mutations located between ROBO1 and ROBO2 increase the risk of microtia in American indigenous populations." (PMID 40809693, 2025). "A recent study uncovered a minimal microtia locus that carries a polymorphic repeat element, which may disrupt ROBO1 and ROBO2 gene expression in the auricle and be responsible for the high incidence of microtia in East Asian and Amerindian populations." (PMID 38690987, 2024).
myeloma (3 papers, 2015 to 2022). "In addition to our report, a recent study investigating multiple myeloma indicated that ROBO1 mutations were frequent and may affect disease prognosis." (PMID 26608094, 2015). "ROBO1 knock-out in myeloma cell lines resulted in impaired engraftment and extramedullary dissemination in immunodeficient mice." (PMID 35847862, 2022). "Roundabout Guidance Receptor 1 (ROBO1) is another molecule involved in the adhesion of myeloma cells to BMSCs." (PMID 35847862, 2022). "Notably, six of the top deregulated genes (NUDT11, PKP2, ROBO1, AGAP1, NAP1L3 and EPDR1) were recently identified as “stem cell” genes in myeloma." (PMID 24913504, 2015). "It is also noteworthy that the 37 top deregulated genes were enriched for the myeloma “stem cell” gene set, including NUDT11, PKP2, ROBO1, AGAP1, NAP1L3 and EPDR1, indicating that “stemness” may play an important role in determining high risk behavior." (PMID 24913504, 2015).
prostate tumors (3 papers, 2013 to 2025). "Moreover, recent studies have demonstrated that phytochemical treatments can increase SLIT2 and ROBO1 expression and inhibit DU145 prostate tumor cells." (PMID 40508075, 2025).
Stroke (3 papers, 2019 to 2025). Sudden impairment of blood flow to a part of the brain due to occlusion or rupture of an artery to the brain. "In animal models, ROBO1 has been associated with better recovery after stroke via Slits’ role in angiogenesis and neurogenesis." (PMID 38103737, 2024). "Data in the present study indicate a robust effect of combined XSEC and EE on up-regulating the protein expression levels of Netrin-1 and Robo-1 in the peri-ischemic brain tissues after stroke." (PMID 31354412, 2019). "Meanwhile, axonal guidance signaling Netrin-1 and Robo-1 would be expected to participate in the beneficial effects of the combined actions of XSEC and EE on angiogenesis and neurogenesis in the ischemic brain after stroke." (PMID 31354412, 2019).